CRP (C-reactive protein)
Diseases named in the same sentence as CRP in open-access papers (continued):
Sharing a sentence is not in itself a finding about the gene and the disease.
infection (continued). "Interestingly, the trends for C-reactive protein (CRP) and leukocytes (both markers of infection and inflammation) did not display similar trend: the feature contribution of CRP was generally high and the feature contribution for leukocytes was generally low." (PMID 38438861, 2024). "During the assessment, the absence of infection indicators such as fever, elevated white blood cell counts, normal erythrocyte sedimentation rate, CRP, and leptomeningeal enhancement in MRI was akin to chasing elusive shadows in the realm of diagnostic uncertainty." (PMID 39104968, 2024). "WBC, CRP and total IgM are all infection-related indicators, of which total IgM indicates a recent infection and IgM does not pass through the placenta, when IgM is increased, it suggests that the fetus may be infected." (PMID 38373935, 2024). "There were no large fluctuations in risk between model 2 and model 3 in this research, suggesting that the risk of NRDS was not increased by adjusting for either potential infection-related factors (WBC/CRP/ total IgM) or maternal status, and was more influenced by demographic factors (GA/weight)." (PMID 38373935, 2024). "Therefore, serum ESR and CRP are used as the first line of screening for PJI; however, surgeons should keep in mind that negative results cannot rule out infection and should investigate with further tests if there is a possibility of infection." (PMID 39493345, 2024). "C-reactive protein (CRP) is an established clinical marker; its concentration in the circulation rises in response to infection and non-infectious inflammation, following increased secretion of inflammatory cytokines, particularly interleukin 6, by macrophages and T cells." (PMID 38188655, 2024). "Other reviews have suggested that inflammatory markers, such as CRP and ESR, may help detect potential infections—especially spinal infections—and, although these markers have low specificity, they serve as early indicators that can aid in preventing complications." (PMID 39594253, 2024). "First, since we were not able to extract the clinical information of individuals in the public data sets, the diagnostic efficacy of theclassifier was not compared with the traditional infection indicators used in clinics, such as CRP, which reduces the reliability of our results." (PMID 38780016, 2024). "Studying the range of values of OPG and CRP in the 2 infection groups (bacterial and viral) and control group, we plotted the densities of OPG, and CRP and we observed, in the case of OPG, a much bigger overlapping values between viral, bacterial and control cases, compared to CRP." (PMID 38509997, 2024). "ESR and CRP are acute markers usually elevated after surgery without any source of infection." (PMID 39493345, 2024). "In particular, CRP was similar in patients with no infection and confirmed VRI." (PMID 38087175, 2024). "While WBC, PCT, and CRP are common inflammatory markers that still play a significant clinical role, they may not fully reflect the body’s infection status due to various factors." (PMID 39026204, 2024). "Elevation of CRP biomarker could take 24–48 h in case of infection and we have no explored the number of patients in this situation in our study." (PMID 38530466, 2024). "Some patients had inflammation and infection markers such as erythrocyte sedimentation rate, CRP, and PCT, but these could not be analyzed consistently due to the lack of uniformity in data availability." (PMID 38510456, 2024). "When CRP levels are elevated only slightly, as in the case of post-ACLR patients, it is sometimes difficult to judge whether the increase is due to surgical invasion or postoperative infection." (PMID 39539898, 2024). "However, neither an increased CRP- nor an elevated PCT-level are specific for infections, as they can both be elevated by non-infectious factors as well." (PMID 38517573, 2024).
infection (continued). "However, in our study, the concentration of CRP remained at high level in the IAI group, but decreased significantly 24 h after anti‐infection in IAE group, which is similar to previous studies, demonstrating that CRP rapidly decreased after reaching its peak in anti‐infection effective group." (PMID 38967137, 2024). "In another study, no significant influence of the CRP level on infection was observed." (PMID 39063921, 2024). "Consistent with this, the subgroup analysis results of this study also showed that for AECOPD patients with high CRP levels, antibiotic treatment can reduce the acute exacerbation rate 30 days after discharge, even if the patient does not have any obvious signs of infection." (PMID 38799157, 2024). "For instance, leukocytosis may be observed in patients on steroidal treatment, but CRP is unlikely to be raised in the absence of an infection." (PMID 39057774, 2024). "CRP is sensitive but not specific to infection or any specific infection site." (PMID 38542009, 2024). "Infection was excluded due to negative C-reactive protein (CRP) and procalcitonin (PCT) values." (PMID 39238746, 2024). "Moreover, serum CRP levels are not a marker specific to cancer cachexia, and they can also be elevated by infection and cancer treatment, including cytotoxic anticancer agents and radiotherapy." (PMID 39765960, 2024). "It is reported that the diagnostic accuracy of PVR in patients with fracture-related infection was no less significant than that of ESR or CRP, suggesting that PVR could function as an auxiliary diagnostic biomarker of fracture-caused infection." (PMID 38741113, 2024). "Cooling may lead to a late peak in CRP in the absence of infection, and the use and duration of prophylactic antibiotics in infants with HIE undergoing TH is still a matter of controversy." (PMID 38225562, 2024). "We did see a significantly higher CRP and trending higher ESR for patients with failure of infection eradication which aligns with the idea that the higher ESR and CRP may coincide with the severity of infection although these lab values are historically more useful in chronic PJI." (PMID 38247607, 2024). "No patients had active infection at the time of CRP level measurement." (PMID 39835329, 2024). "However, that study only reports the CRP levels in healthy individuals and does not address how the CRP levels respond to infection across different age groups." (PMID 39452762, 2024). "Therefore, if blood samples are not performed within the first days post-infection, the CRP and SAA levels migth already have decreased below physiological levels." (PMID 39237955, 2024). "Consequently, only a part of the infants with suspected infections had blood sampled for bacterial cultures and assessment of CRP levels and since the trial was not blinded, we cannot exclude possible bias of clinicians." (PMID 38775927, 2024). "In conclusions, our real-world data analysis suggested that C-reactive protein and white blood cell may not be reliable indicators for predicting mortality in children with presumed infection." (PMID 39015209, 2024). "In the findings of this study, patients with PI exhibited elevated postoperative infection markers compared to patients without PI, such as increased levels of postoperative white blood cells and C-reactive protein, as well as a higher incidence of postoperative fever." (PMID 39011051, 2024). "Conventional biomarkers such as procalcitonin and C-reactive protein have been shown to lack sufficient discriminatory power, while other studies support that metabolomics and lipidomics profiles can separate infection from non-infection." (PMID 39369060, 2024). "Elevated CRP levels were a result of MI rather than an indication of infection." (PMID 38921434, 2024).
infection (continued). "The panelists commented that decisions about changes in the empiric antibiotic regimen may be taken based on the kinetics of serum CRP (a rising curve suggesting a new infection and a flat curve suggesting no new infection)." (PMID 39694764, 2024). "The Mann–Whitney U test was applied to assess the differences between groups belonging to a dyad (group 1, N = 23) or not (group 0, N = 85) in relationship to breastfeeding, CRP and infections, provided by the best (RF) model in the test, to generate unbiased results." (PMID 38535296, 2024). "The maximum concentration of plasma CRP was higher in neonates with confirmed or clinically diagnosed infection as compared to those not subjected to antibiotic therapy or those with empirical antibiotic administration but in whom infection was later ruled out." (PMID 39340678, 2024). "Notably, the concentration of CRP and PCT were not meaningful risk factors in this study, partly because patients in our cohort all burned in severe infection and inflammations so the effect of the inflammatory response is less obvious, if existing." (PMID 39659367, 2024). "CRP levels increase in both infection-induced and non-infectious inflammatory responses." (PMID 36832265, 2023). "However, patients with slightly elevated CRP levels without obvious signs of infection were allowed to proceed to transplantation." (PMID 37370833, 2023). "A 2016 study in the pediatric population showed how a CRP < 5 mg/L rules out severe infection and could be used by primary care physicians to avoid unnecessary hospital referrals." (PMID 37324112, 2023). "A CRP value of 100 mg/l or higher has not been validated as a marker of severe infections." (PMID 37314998, 2023). "Infection may be detected early in DKA patients by using biomarkers like procalcitonin, serum lactate, procalcitonin/lactate ratio, white blood cell count, neutrophil/lymphocyte ratio, and C reactive protein." (PMID 37510185, 2023). "However, the study reported that neutrophil percentage, leukocyte count, and CRP were more in the case of DKA with infection when compared to patients without infection." (PMID 37510185, 2023). "However, most of the studies were conducted on noninfectious DPLD diagnosis, there was little literature on the application of TBCB-based CRP strategy in the diagnosis of all DPLD including infection-related and non-infection related DPLD." (PMID 37408612, 2023). "Since in our study CRP elevation was also an adverse factor for survival in CMML patients without infection, one is tempted to speculate that inflammation per se may promote progression of this disease." (PMID 36441359, 2023). "This may be attributable to the fact that many severe patients were included in the nonrespiratory infection group because CRP was high." (PMID 36973757, 2023). "Furthermore, we did not include laboratory parameters or vital signs related to infection parameters such as C-reactive protein or body temperature." (PMID 37566601, 2023). "Despite the potential benefits of using CRP to predict infections, some studies suggest that it may not be a reliable diagnostic marker for IAI." (PMID 37189111, 2023). "Even when the symptoms were not obvious at early stages, there could be an increase in infection-related indicators such as CRP and NEUT%." (PMID 38034684, 2023). "As opposed to the synovial protein, the plasmatic concentration of PTX3 had poor diagnostic value, likely due to this long pentraxin being mainly synthesized in loco at sites of infection, unlike the short pentraxin CRP that is systemically produced by the liver in response to IL-6." (PMID 36769703, 2023). "Erythrocyte sedimentation rate (ESR) and C-reactive protein (CRP) are recommended as essential indicators for the diagnosis of PJI by the American Academy of Orthopaedic Surgeons (AAOS) and the Musculoskeletal Infection Society (MSIS) guidelines due to their superior sensitivity and specificity." (PMID 38026480, 2023).
infection (continued). "Time-dependent analysis of CRP showed a significant increase in this biomarker in the 48 h before the day of infection diagnosis, whereas the CRP level in non-infected patients remained almost unchanged and steady during the days before the event of interest (p = 0.009)." (PMID 37834754, 2023). "The study interventions involved measuring and comparing serum levels of 25-hydroxyvitamin D3, parathormone, calcium, phosphate, alkaline phosphatase, complete blood count parameters, and C-reactive protein of the preschool children with rotaviral diarrhea and the controls without the infection." (PMID 36918811, 2023). "CRP POCT can help decide whether a serious infection can be ruled out, before deciding on further treatments or management, when clinical assessment is unconclusive." (PMID 37900677, 2023). "Serial serum measurements revealed a high prevalence of abnormal CRP levels (9 of 10 children) in the absence of an intercurrent infection, defined as negative bacterial and viral studies 7 days before and after a CRP, that remained elevated for a prolonged period." (PMID 36645080, 2023). "CRP, being a non-specific marker, can be elevated secondary to infection, trauma, and inflammation." (PMID 37759159, 2023). "Current Australian guidelines on DFI care suggest investigations such as CRP, probe to bone and plain x-rays are ordered as part of routine assessment pathway, whilst blood cultures are not ordered unless clinically indicated (Grade 4 Infection)." (PMID 37858102, 2023). "An early diagnosis of infections may be challenging since specific symptoms of DKA are like that of infection, like fever, a raised leukocyte count, neutrophil percentage, C reactive protein (CRP), and procalcitonin (PCT)." (PMID 37510185, 2023). "In this prospective study, we evaluated the clinical biomarkers (NLR, LDH, ferritin, CRP, procalcitonin, and D-dimer) during the acute phase of SAR-CoV-2 infection which will help to predict long-term SARS-CoV-2-specific IgG antibody response as late as 6 months following natural infection." (PMID 37293303, 2023). "The PCT and CRP values observed on the day of the infection diagnosis were larger (p < 0.001) than those observed on day 11 after ICU admission in patients without secondary infections." (PMID 37887237, 2023). "Moreover, in the phase II clinical trial, patients treated with a CRP ASO demonstrated no increase in infections compared to control patients." (PMID 36468184, 2023). "All patients had normal CRP levels, which indicated the absence of any active infection." (PMID 37602123, 2023). "Although, the primary aim of the current study was to identify molecular changes associated with infection/inflammation in both mice and human, the concomitant increase in LCN2, CRP and IL6, that we found in this study, might aid in recognizing preterm infants experiencing infection." (PMID 37496672, 2023). "However, as a limitation, it is uncertain if the inflammatory process was acute or chronic since alpha 1-acid glycoprotein (AGP) which is more reliable in distinguishing past from present infection than CRP was not assayed." (PMID 37507740, 2023). "Regardless of CRP level, hospitalization was needed in 86–90% of the infection episodes." (PMID 37314998, 2023). "In contrast, CRP only showed a tendency to slightly increase during the first 2 days post infection (as compared to inflammation of non-infectious origin) and could not help clearly differentiate between the two cases." (PMID 37296737, 2023). "Minimally invasive posterior fixation alone did not improve C-reactive protein concentration even ~2 weeks postoperatively, and infection control was considered insufficient in three patients (9.6%) who required anterior lesion debridement and autogenous bone grafting with the fibula or iliac bone." (PMID 36769580, 2023). "CRP and white blood count show no signs of infection or inflammation." (PMID 38035016, 2023).
infection (continued). "Although the reasons for the elevated CRP concentration in the non-migrant group remain unclear, a higher prevalence of chronic or recurrent infection in non-migrants could a potential reason." (PMID 37664733, 2023). "In this study, no increase in serum CRP levels was observed on day 180 post-infection." (PMID 37508953, 2023). "We could not include CRP since in the included cohorts it was most often sampled when there was suspicion of infection; therefore, data was available only for a small subset, and likely showing strong selection bias." (PMID 37034013, 2023). "However, elevated CRP levels and WBC count are common during the early postoperative period; therefore, these studies are not helpful during the first 2 weeks after surgery; following that period, consistently high levels are more indicative of an infection." (PMID 36829589, 2023). "Further, in those clinically diagnosed with a postnatal infection in the absence of antenatal infection concerns, IL-6 increases before CRP, emphasizing a potential role for expanded biomarker screening if antibiotics are initially avoided in infants delivered for maternal indications." (PMID 37606448, 2023). "Low POC CRP levels do not necessarily rule out serious infections." (PMID 36333682, 2022). "Both studies showed that PCT levels might not be as useful as a biomarker as CRP in less severe or localized infections." (PMID 36295492, 2022). "Most studies showed significant differences between the levels of PCT and CRP between infectious and non-infectious patients, which may help identify infections." (PMID 36475186, 2022). "Based on systematic literature review, postoperative prophylactic antibiotic was not indicated, unless symptoms of infection (ill-appearing child, fever, neutrophilic leukocytosis, elevated C-reactive protein or erythrocyte sedimentation rate) were encountered." (PMID 35089125, 2022). "The authors concluded that C-reactive protein in the absence of clinical signs of infection might be used as an indicator of short remaining lifetime." (PMID 35184630, 2022). "Though PCT exhibits higher specificity for bacterial infection than CRP and other traditional markers do, its level may also be elevated in conditions without infection." (PMID 34983420, 2022). "However, CRP has its limitations as it is a non-specific marker and its levels can dramatically increase in cases of infection and tissue damage." (PMID 35888650, 2022). "Furthermore, CysC is affected by inflammation and infection; however, we did not adjust CysC for this as CRP was not available in follow-up." (PMID 36555881, 2022). "Therefore, the higher CRP level and PCT level and lower ALB level in the PJP+CMV group may also be representative of more severe infection and serious inflammatory response." (PMID 35479953, 2022). "All patients had complete remission of their infection after NPWTi-d treatment following implant removal; the remission parameters were resolution of the clinical signs of infection (redness, swelling, pain), decreased serum CRP and serum leukocytes and absence of pus in the exudate." (PMID 36556274, 2022). "However, TNF-alpha values showed no decisive results, leading to the conclusion that CRP values in this study are not triggered by infection." (PMID 36430283, 2022). "Furthermore, heart rate, temperature, total NEWS score, and CRP were all significantly higher in the infection group compared to the non-infection group." (PMID 35406374, 2022). "Second, other serum parameters related to infection, such as white blood cells or C-reactive protein, could not be investigated and there were many missing values for the cause of fever." (PMID 36557064, 2022). "In contrast to outpatients, where other infections are likely more common (and of higher severity) like in inpatients CRP, will have decreased specificity and may not be as useful yet more data are needed." (PMID 35760050, 2022).